KRT8 (keratin 8)
Description:
Structural component of intermediate filaments in simple epithelial cells. Together with its obligate type I partner KRT18, contributes to the formation of the keratin intermediate filament network that provides mechanical stability and resilience to epithelial cells. Also involved in maintaining epithelial integrity and protecting cells from non-mechanical stress, such as apoptosis (By similarity). Also required for ARHGEF40-mediated actin stress fiber formation and tensional force-induced stress fiber formation and reinforcement. In striated muscle, together with KRT19, may contribute to linking the contractile apparatus to dystrophin at the costameres.
Synonyms: CK-8; K8; CYK8; CARD2; CK8; K2C8; KO
Tractability: Antibody: its Gene Ontology location is reachable by antibodies, with medium confidence. PROTAC: UniProt records ubiquitination sites on it; ubiquitination databases record sites on it; its protein half-life has been measured.
Gene: Protein-coding gene on chromosome 12 (52,897,182 to 52,949,954, reverse strand). Ensembl gene ENSG00000170421.
Subcellular location: Cytoplasm; Nucleus, nucleoplasm; Nucleus matrix; Cytoplasm, cytoskeleton
Subcellular location (Human Protein Atlas): Intermediate filaments
Pathways (Reactome):
Developmental Biology: Developmental Lineage of Mammary Gland Alveolar Cells; Developmental Lineage of Mammary Gland Luminal Epithelial Cells; Formation of the cornified envelope; Keratinization
Gene Ontology:
Molecular function: protein binding; scaffold protein binding
Biological process: epithelium development; intermediate filament organization; negative regulation of hepatocyte apoptotic process; sarcomere organization
Cellular component: cytoplasm; extracellular exosome; intermediate filament; intermediate filament cytoskeleton; keratin filament; nucleus; cytosol; nuclear matrix; apicolateral plasma membrane; cell periphery; cell-cell junction; cytoskeleton; nucleoplasm; sarcolemma; Z disc
Genetic constraint (gnomAD): Loss-of-function variants: 21 observed, 38.26 expected, observed/expected ratio (o/e) 0.55, 90% interval 0.39 to 0.79. The upper end of that interval is the gene's LOEUF score, 0.79, which puts it in group 3 of 6, group 1 being the genes least tolerant of losing a copy. Missense variants: 489 observed, 621.7 expected, observed/expected ratio (o/e) 0.79, 90% interval 0.73 to 0.85. Synonymous variants: 214 observed, 255.11 expected, observed/expected ratio (o/e) 0.84, 90% interval 0.75 to 0.94.
Homologues: Orthologues: chimpanzee KRT8 (99% identical), mouse Krt8 (91% identical), pig KRT8 (90% identical), rat Krt8 (90% identical). Paralogues in human: KRT5 (62% identical), KRT75 (61% identical), KRT6A (60% identical), KRT6B (60% identical), KRT6C (60% identical), KRT3 (58% identical), KRT7 (56% identical), KRT76 (56% identical), KRT1 (55% identical), KRT4 (54% identical), KRT79 (54% identical), KRT2 (54% identical), and 56 more.
Diseases named in the same sentence as KRT8 in open-access papers:
KRT8 is named in the same sentence as 200 diseases in open-access papers, as found by Europe PMC text mining. Sharing a sentence is not in itself a finding about the gene and the disease. The quoted sentences say what the papers report.
breast cancer (100 papers, 2007 to 2026). A primary or metastatic malignant neoplasm involving the breast. "Keratin-8 (KRT8) specifically has been associated with the multiple drug resistance (MDR) phenotype in breast cancer cells, and has been suggested to potentially modulate apoptosis resistance in nasopharyngeal carcinoma." (PMID 29443941, 2018). "Nearly 80% of breast carcinomas exhibit a loss of the differentiation-associated keratin 8 and 18 have generally been associated with a worse prognosis." (PMID 24034496, 2013). "Differentially expressed genes (DEGs) such as KRT8 and KRT18, associated with epithelial function, were highly expressed in these domains, while NUPR1, a prognostic marker in early-stage breast cancer, was upregulated." (PMID 40838787, 2025). "The top five hub genes for the hormone-like community were KRT18, JUP, KRT8, SH2D3A and PDLIM1; KRT18 and KRT8 are luminal markers in breast cancer while JUP (plakoglobin), SH2D3A and PDLIM1 are relatively undescribed in the context of cancer." (PMID 39556603, 2024). "This dataset, comprised of ER-positive, PR-positive, HER2-positive and TNBC, showed a distinct clustering, with multiple EPCAM+ and Keratin-8+ (KRT8) clusters corresponding to the heterogeneous tumor cell populations in each of the breast cancer subtypes." (PMID 36635273, 2023). "KRT8 is overexpressed in breast cancer and involved in epithelial to mesenchymal transition and cancer metastasis." (PMID 33976232, 2021). "Previous studies have shown that KRT8 expression is significantly elevated in various human cancers, including bladder cancer, breast cancer, kidney cancer, pancreatic cancer, and lung cancer." (PMID 30634629, 2019). "Both primary and passaged tumors expressed similar levels of both Keratin 5 and Keratin 8/18, as is observed in basal-like breast cancer." (PMID 30484104, 2019). "BRC-31 breast cancer cells expressed high levels of cdh2, fn1 and vim and low levels of cdh1 and krt-8 compared to BRC-17, 32, 36 and 196 cells." (PMID 29382358, 2018). "This analysis also revealed higher expression of cancer biomarkers such as KRT8 (breast cancer prognosis), FN1 (pancreatic cancer), NQ1 (lung cancer), and PSDM4 (liver cancer) in the Huh-7.4 cell line." (PMID 29221196, 2017). "Four genes from breast cancer stage III network pattern (KRT8, KRT17, KRT18 and HOXC10) physically interact with EGFR, a target gene of Lapatinib Breast cancer drug which is quite similar (greater than 50%) to Paroxetine (repurposed drug from LINCS)." (PMID 26892392, 2016). "Anti-KRT8 antibodies inhibit the urokinase-type plasminogen activator receptor binding and plasmin production by breast cancer cells, increasing tumor invasive potential." (PMID 26398185, 2015). "Expression of keratin 8 and keratin 19 in the estrogen positive (ES+) breast cancer cell lines suggested that these cells had originated from luminal epithelial cells." (PMID 23599813, 2013). "STAT1-/- ERα+ mammary tumors also showed elevated transcription of genes characteristic of luminal breast cancers (for example, keratin 8, keratin 18, XBP1, GATA3, MYB, AREG, and FOXA1)." (PMID 22264274, 2012). "For detection of Keratin 8/18 and Nanog protein expression, primary mammary tumor cells were grown under mammosphere culture conditions for 7 days." (PMID 22992387, 2012). "Human breast cancer cells integrated in chimeric outgrowths expressed the human mammary luminal marker keratin 8 (hK8)." (PMID 23155468, 2012). "Breast cancer specimens that expressed keratin 8/18, markers of luminal epithelial cells, were classified as luminal breast cancers, while those that expressed keratin 5/6, markers of basal epithelial cells, were classified as basal breast cancer." (PMID 27918430, 2016). "KRT8 is highly expressed in a multidrug-resistant breast cancer cell line, MCF-7/MX compared to parental MCF-7 cells, resulting in enhanced cell adhesion to the extracellular matrix, which could contribute to the mechanism of resistance." (PMID 27711225, 2016).
breast cancer (continued). "The mammary tumors predominantly express the luminal lineage marker keratin 8/18." (PMID 22992387, 2012). "Interestingly, the expression of Pik3caH1047R in basal Lgr5 + and luminal Krt8 + cells induced mammary tumors of distinct histotypes on average after 108 and 78 days, respectively, indicating that aggressiveness and latency greatly depend on the identity of the cell-of-origin." (PMID 40676433, 2025). "Indeed, changes in keratin expression during breast cancer invasion (that is, from a luminal keratin 8 to a basal keratin 14) (ref.46) could also affect the mechanical properties and responsiveness of the keratin network to external signals." (PMID 37709930, 2023). "In addition, four cytokeratin genes (KRT8, KRT16, KRT17, and KRT19) and eight tumor-associated genes (TERT, MUC16/M17S2/CA125, CD44, TWIST1, TACSTD1/EpCAM/CD326/ESA/HEA125/GA733, DPP4/CD26, ESR1, and PGR), were upregulated in CRC and breast cancer samples." (PMID 29882767, 2018). "Expression of Pik3ca-mutations in luminal cells (e.g., using promoters MMTV, WAP and Krt8) mostly evoked adenosquamous mammary carcinomas, which exhibited mixed-lineage features highlighted by the presence of KRT14/KRT8 & KRT18 double-positive cancer cells." (PMID 40676433, 2025). "The tumor-specific marker genes (i.e. EPCAM, KRT8, EPCAM, B2M, FCA1 and KRT19) were also highly expressed in the tumor regions of prostate, colorectal, liver cancer, pancreas and breast cancer." (PMID 36243975, 2023). "To model human breast cancers with low IGF1R expression, we also generated a mammary luminal epithelial lineage-specific Igf1r knockout mouse driven from a tamoxifen-inducible Keratin 8 (K8)-Cre, referred to as the K8iKOR line." (PMID 36568144, 2022). "Five of these antigens (VPS35, ARPC2, SERBP1, KRT8, and PDIA6) were selected because they inhibited human breast cancer survival across two aggressive breast cancer subtype cell lines (HER2 positive and triple negative)." (PMID 33976232, 2021). "The plakoglobin (JUP), KRT8, KRT18, KRT19, CLDN4, and EPCAM, which their role in breast cancer metastasis was demonstrated in previous studies, are EMT markers." (PMID 34801010, 2021). "Four of the antigens (VPS35, SERBP1, KRT8, and PDIA6) decreased growth of the tumors in both mouse mammary tumor models." (PMID 33976232, 2021). "We used primers for the gene sequences of UBB, ESR1 (for luminal or ER/PR+ cancer cells), HER2 and GRB7 (for HER2+ cancer cells), EPCAM, KRT7, KRT8, KRT18, and KRT19, all of which have been commonly discussed for the purpose of breast cancer diagnosis." (PMID 28936247, 2015). "Overexpression of cytokeratins such as KRT8 was shown to enhance adhesion of MCF7 cells to the extracellular matrix and correlate with drug resistance of breast cancer cells." (PMID 20543960, 2010). "The four different ESR1 probes on the array defined two primary ESR1-associated probe set clusters, including genes (for example, GATA3, KRT8, KRT18) commonly used to define luminal-type breast cancers." (PMID 17850661, 2007). "Using cell surface biotinylation of intact SKBR3 breast cancer cells and Caco2 CRC cells, we demonstrated that the streptavidin (SA)-binding, biotinylated proteins from both cell lines included KRT19 and KRT8, a type II keratin protein that dimerizes with KRT19." (PMID 35046049, 2022). "In the dataset of 50 breast cancer lines TF expression clustered with higher levels of basal-marker vimentin, keratin KRT5/14 and caveolin-1 (CAV1) but lower levels of luminal-marker keratin KRT8/18, ERBB3 and ESR1." (PMID 28938620, 2017). "We found that TF expression in breast cancer lines and tumors closely clustered with higher levels of EMT (high vimentin/low E-cadherin) and classical basal-type biomarkers KRT5, KRT14 and caveolin-1, while it clustered with lower levels luminal-type biomarkers KRT8, KRT18, ERBB3 and ESR1." (PMID 28938620, 2017).
breast cancer (continued). "Clusters negative for EPCAM and KRT8, corresponded to the cells of the TME, like endothelial cells (CD31+), immune cells (CD45+) and fibroblasts (COL1A1+) and were present in all breast cancer subtypes." (PMID 36635273, 2023). "Analysis of the TCGA breast cancer database shows a highly significant correlation between CD163 or CD68 and SIGLEC9 but not with the epithelial markers, EPCAM or KRT8." (PMID 33149188, 2020). "Godfroid et. al. further demonstrated the presence of cytokeratins KRT8, KRT18, and KRT19 on the outer surface of established human mammary carcinoma cells but not normal mammary cells." (PMID 20543960, 2010). "Interestingly, comparative analysis of the basal‐like vs. luminal breast cancer cell types markers in ABI1 KO mice showed that the genes of basal‐like cells (Krt14, Vim) are responded to Abi1 depletion, however luminal cell type genes markers (Krt8, Krt18, Sox9, Estr1) do not." (PMID 34967509, 2022).
prostate carcinoma (34 papers, 2007 to 2025). A carcinoma that arises from epithelial cells of the prostate gland. "Previous studies have shown that NAT10 can promote the proliferation, migration, and metastasis of prostate cancer cells by regulating KRT8 through ac4C acetylation." (PMID 41203621, 2025). "With respect to KRT8, previous studies have suggested its potential role in gastric cancer or prostate cancer." (PMID 39991825, 2025). "In PCa, expression of KRT8, KRT18, and KRT19 by tumor cells disseminated to the bone, is associated with a worse prognosis; KRT18 and KRT5 expression correlates with metastases and hormone-escaped prostate carcinomas, respectively." (PMID 36033462, 2022). "Conversely, in the other study, KRT8, KRT15, KRT19, KRT34, and KRT80 were found to be enriched in African American prostate cancer samples." (PMID 40104216, 2025). "In prostate cancer, NAT10 promotes metastasis by acetylating Keratin 8 (KRT8) mRNA to enhance its stability, downregulating E-cadherin and upregulating N-cadherin protein expression, thereby activating EMT." (PMID 40881352, 2025). "In prostate cancer (PCa), NAT10 enhances the stability of high mobility group AT-hook 1 (HMGA1) and Keratin 8 (KRT8) by acetylating their mRNAs, hence accelerating cell cycle progression to improve cell proliferation and enhancing EMT progression to facilitate cell migration, respectively." (PMID 41316475, 2025). "The preponderance of NE and non-NE prostate cancer at end stage varied among individual mice, but some TKO-Nicd1 mice had non-NE adenocarcinoma (KRT8+SYP–INSM1–) as the predominant end-stage tumor." (PMID 39024561, 2024).
gastric cancer (23 papers, 2015 to 2025). A primary or metastatic malignant neoplasm involving the stomach. "A recent study suggested that in clear cell renal cell carcinoma and gastric cancer, KRT8 upregulation promotes tumor metastasis and associated with poor prognosis." (PMID 30813883, 2019). "In gastric cancer, higher KRT8 expression also associates with poorer prognosis." (PMID 33777753, 2021). "As reported, KRT8 plays a key role in gastric cancer and renal cancer by regulating cell migration and invasion." (PMID 35664775, 2022). "KRT8 is upregulated in clear cell renal cell carcinoma, gastric cancer, breast cancer, and lung cancer." (PMID 35664775, 2022). "Phosphorylated KRT8 in serine 431 plays an important role in human pancreatic and gastric cancer cells, because it induces keratin reorganization and consequently enhanced migration of tumor cells." (PMID 32337254, 2020). "In some cancers, upregulation of KRT8 has been considered a valuable prognostic marker, including for gastric cancer, oral squamous cell carcinomas, and ccRCC." (PMID 30634629, 2019). "Notably, MAM Domain Containing Glycosylphosphatidylinositol Anchor 2 (MDGA2) also showed the same differential expression but was only studied in gastric cancer and keratin 8 (KRT8), less expressed in proliferating BC cells, was also present in this group." (PMID 40124331, 2025). "On the other hand, KRT8 has been found to promote gastric cancer progression." (PMID 38495507, 2024). "In gastric cancer, high KRT8 expression is illustrated to promote tumor progression and metastasis." (PMID 36522691, 2022). "KRT8 overexpression was connected to gastric cancer cell proliferation and progression in vitro." (PMID 35328735, 2022). "Krt8 expression has been found to be increased in some carcinomas and promotes tumor progression and metastases in gastric carcinoma in particular." (PMID 34122126, 2021). "have found that KRT8 can facilitate gastric cancer progression and metastasis." (PMID 32519739, 2020). "Krt8 has been found to have increased expression in some carcinomas and to promote tumor progression and metastases in gastric carcinoma in particular, but it has also been involved in alveolar epithelial progenitors in lung regeneration and increased replication of respiratory syncytial virus." (PMID 34122126, 2021). "Keratin 8 (KRT8) overexpression enhanced cell proliferation and migration in gastric cancer and lung cancer, while its decreased expression markedly inhibited cell proliferation, migration, and EMT process." (PMID 36299414, 2022). "KRT8 mRNA and protein expression has been found to be upregulated in gastric cancer (GC) tissues, and its high expression has been observed to promote the cell progression and metastasis of GC cells and produce unfavorable outcomes for patients with GC." (PMID 30634629, 2019).
lung carcinoma (19 papers, 2008 to 2024). "The KRT8 gene, encoding a protein known as Keratin 8, plays a significant role in the realm of lung cancer diagnosis and treatment." (PMID 38356715, 2024). "KRT8 has been identified as a target of cisplatin, and the KRT8/AKT signaling pathway plays a crucial role in lung cancer metastasis by regulating the function of cancer‐associated fibroblast in the tumor microenvironment." (PMID 39036344, 2024). "Hypermethylation of genes such as COX7A1, TNFRSF1B, and BDNF, as well as hypomethylation of genes such as CDC6 and KRT8, may be associated with lung cancer compared to benign nodules." (PMID 39036344, 2024). "KRT8, a type II intermediate filament protein, is over‐expressed in various cancers, including lung cancer." (PMID 39036344, 2024). "Meanwhile, the colony formation assay showed that the proliferation of lung cancer cells was suppressed by KRT8 knockdown." (PMID 35664775, 2022). "We further demonstrated that CAFs modulate lung cancer cell metastasis through IL-6/STAT3 and KRT8/AKT pathways, however, the underlying mechanism is not fully understood." (PMID 34552063, 2021). "Oncomine analysis of lung cancer versus normal tissue also confirmed that KRT8 was significantly overexpressed in LUAD." (PMID 30634629, 2019). "Using TCGA RNA-seq data, we first analyzed KRT8 mRNA expression in both lung cancer tissues and normal tissues." (PMID 30634629, 2019). "Moreover, in the cell scratch assay, KRT8 knockdown significantly impaired cell migration compared to the control group, demonstrating its role in promoting lung cancer cell migration." (PMID 38356715, 2024). "Thus, the Transwell migration and invasion assay were applied in HCC827 and H1975 to explore the effects of KRT8 knockdown on lung cancer cell motility." (PMID 35664775, 2022). "Overall, these data demonstrated that KRT8 knockdown could inhibit lung cancer cell migration and invasion in vitro." (PMID 35664775, 2022). "The high expression of KRT8 promoted EMT and migration of lung cancer cells and was positively related with poor survival of patients with LUAD." (PMID 35664775, 2022). "The CCK-8 and colony formation assay were used in two human lung cancer cell lines (HCC827 and H1975) to explore the effects of KRT8 knockdown on cell proliferation." (PMID 35664775, 2022). "KRT8 was used for cancer prognosis, including for ADC patients, whereas KRT10 was found to be a useful biomarker for the treatment response in lung cancer." (PMID 35512017, 2022). "Following this, we tried to characterize KRT8 protein expression in normal tissues and in lung cancer tissues by analyzing IHC staining images from the HPA database and found that normal tissues had no KRT8 staining (left)." (PMID 30634629, 2019).